LTB (lymphotoxin beta)
Diseases named in the same sentence as LTB in open-access papers (continued):
Sharing a sentence is not in itself a finding about the gene and the disease.
cancer (15 papers, 2016 to 2025). A tumor composed of atypical neoplastic, often pleomorphic cells that invade other tissues. "Notably, PPIA-BSG and LTB-LTBR have been linked to a positive correlation in various cancers and are associated with poor prognosis." (PMID 39013860, 2024). "The analysis revealed that PPIA-BSG and LTB-LTBR were recurrent ligand-receptor pairs mediating the recognition of cancer epithelial cells by immune cells." (PMID 39013860, 2024). "The TNF superfamily member gene LTB has pleiotropic functions, including cancer inflammation, tertiary lymphoid structure and NK cell development." (PMID 36230839, 2022). "In contrast to parenchymal MAMs, the activation state of dural MAMs remained unaffected by the overexpression of LTβ in cancer cells." (PMID 27203741, 2016). "We hypothesized that down-regulated LTB (immune gene) modulated by PAX5 (TF) in STSs may have the capability of inducing cancer cell metastasis in patients with STS." (PMID 33397394, 2021). "Alternatively, homotypic LTβ/LTβR interactions between cancer cells may alter their cytokine profiles, which may have an indirect effect on iNOS and inflammatory cytokines in MAMs." (PMID 27203741, 2016). "Notably, the overexpression of LTβ in cancer cells significantly reduced the expression of iNOS, TNFα and IFNγ in parenchymal MAMs by 35%, 79% and 25%, respectively, implicating LTβ in polarization of MAMs towards the M2 state." (PMID 27203741, 2016). "This suggests that the downregulation of iNOS, TNFα and IFNγ in MAMs in our model may occur through a direct interaction between LTβ on cancer cells and the LTβR on MAMs." (PMID 27203741, 2016). "Based on comprehensive bioinformatics analysis and preliminary experiments, we hypothesized that excessively downregulated LTB (an immune gene) modulated by PAX5 (a TF) in STSs induced cancer cell metastasis in patients with STS by modifying the haematopoietic cell lineage pathway." (PMID 33397394, 2021). "Conversely, the different cell lines showed variable expression of LTB and IL18R1, as already reported in different epithelial and carcinoma cells." (PMID 35201443, 2021). "On the other hand, although HCV infection reportedly induces LTB expression in human hepatocytes, the significance of LTB in human cancer cells, and not in lymphocytes infiltrating the cancer stroma, has remained unclear in both the liver and other organs." (PMID 36348017, 2023). "Moreover, DNA methylation alterations of the LTB gene in human cancers have not been reported previously." (PMID 36348017, 2023).
infection (14 papers, 2008 to 2024). The state of being infected such as from the introduction of a foreign agent such as serum, vaccine, antigenic substance or organism. "We next characterized brain-sequestered leukocytes, in wild-type and TNF deficient mice with severe neurological symptoms after PbA infection and in LTβR or LTβ deficient mice at the same day after infection." (PMID 18612394, 2008). "The expression of Ltβ mRNA was significantly elevated in the tissue on day 8 and day 23 post LuCAdV5 infection." (PMID 39355243, 2024). "Therefore, in this study we used LTβ−/− mice that lack most peripheral lymph nodes to determine the requirement of the draining lymph nodes for the effective establishment of infection after intradermal (ID) inject with T. brucei." (PMID 32582198, 2020). "Moreover there is a group of molecules, including LTA, LTB, IL21, IFNAR2, CXCR3, IL17F and CD40LG, whose expression increased over the course of USA300 infection." (PMID 25719526, 2015). "However, human ETEC isolates sometimes carry a version of LTB identical in amino acid sequence to porcine LTB, and therefore, the relevance of this binding to human infection should not be completely dismissed." (PMID 22069646, 2010).
cardiovascular disease (2 papers, 2017 to 2022). "Six genes (TKT, TCF4, SWAP70, DDHD2, ARHGAP31, and LTB) showed significant associations of genetic variants with the risk of cardiovascular disease." (PMID 36204511, 2022).
head and neck tumors (1 paper, 2023). "In head and neck tumors, research has found that LTB can inhibit cell proliferation and invasion, and induce cell apoptosis." (PMID 37884883, 2023). "Furthermore, LTB can also suppress the growth and metastasis of head and neck tumors by activating the immune system." (PMID 37884883, 2023).
inflammatory myopathies (1 paper, 2025). "Several tumor necrosis factor (TNF) superfamily genes (TNFSF8, LTB, TNFSF12, TNFSF13B, TNFSF14, TNFSF13, EDA) were upregulated, with LTB and EDA reaching higher levels than in other inflammatory myopathies." (PMID 41441888, 2025).
LTB also shares sentences with these, for which no sentence is quoted: Cirrhosis (2 papers); acne vulgaris (1); acquired immune deficiency syndrome (1); alcoholic liver diseases (1); allergies (1); anemia (1); Arthritis (1); atherosclerosis (1); autoimmune hepatitis (1); B cell deficiency (1); bacterial diseases (1); bladder cancer (1); blood cancers (1); cervical cancer (1); chronic hepatitis C (1); chronic kidney disease (1); chronic periodontitis (1); cutaneous T-cell lymphoma (1); Dengue (1); endometrial cancer (1); Fanconi anemia (1); fungal infections (1); Granuloma (1); hepatitis B virus infection (1); hepatitis C (1); inflammation (1); leptospirosis (1); lipomatosis (1); liver diseases (1); multiple myeloma (1).
A further 12 diseases each share a sentence with LTB in 1 paper.